IL10 (interleukin 10)
Diseases named in the same sentence as IL10 in open-access papers (continued):
Sharing a sentence is not in itself a finding about the gene and the disease.
appendicitis (9 papers, 2018 to 2025). Acute inflammation of the vermiform appendix. "We discovered that preoperative serum levels of IFN-γ, IL-5, IL-6, IL-8, and IL-10 hold diagnostic value in staging pediatric acute appendicitis." (PMID 40150581, 2025). "In contrast, a recent study in post-operative appendicitis patients revealed reduced IL-10 concentrations after exposure to blue light when compared to standard hospital lighting." (PMID 39435315, 2024). "Children with complicated appendicitis had significantly higher concentrations of serum IL-6 and IL-10, and lower of TNF-β." (PMID 38409170, 2024). "The aim of the present study was to evaluate how the Th1 and Th17-associated cytokines IL-1α, IL-1β, IL-2, IL-6, IL-10, IL-17A and tumor necrosis factor beta (TNF-β) are associated with the risk of complicated appendicitis in children." (PMID 38409170, 2024). "A similar cytokine pattern has earlier been described in cases of complicated appendicitis (IL-6, IL-17alfa and IL-10), as well as a more prominent Th1 inflammatory pattern." (PMID 36013568, 2022). "Serum IL-6 and IL-10 were significantly elevated during acute appendicitis, whereas IL-8 was significantly lower during appendicitis." (PMID 33060696, 2020). "There was a clear trend towards higher IL-10 responses in PBMCs from patients with a history of complicated compared to uncomplicated appendicitis, and responses towards a number of specific stimuli were significantly elevated." (PMID 33060696, 2020). "Serum levels of IL-10 were significantly elevated in children with perforated appendicitis." (PMID 40150581, 2025). "Some investigations have discovered a correlation between IL-10 and the severity of appendicitis." (PMID 40150581, 2025). "High serum concentrations of IL-6 were associated with an increased risk of complicated appendicitis in children, whereas serum concentrations of IL-1α, IL-1β, IL-2, IL-10, IL-17A and TNF-β were not." (PMID 38409170, 2024). "This prospective cohort study aimed to evaluate the association between serum concentrations of the Th1-associated cytokines interleukin (IL)-1α, IL-1β, IL-2, IL-6, IL-10, IL-17A and tumor necrosis factor beta (TNF-β) and the risk of complicated appendicitis in children." (PMID 38409170, 2024). "In addition to be an important inflammatory biomarker for acute appendicitis, IL-10 has also been found in other studies to be increased during severe appendicitis." (PMID 34677379, 2021). "Serum IL-10 was significantly higher in gangrenous appendicitis." (PMID 33060696, 2020). "Stronger IL-10 responses were found following complicated appendicitis." (PMID 33060696, 2020). "When comparing IL-10 expression between Group II and Group III, an increase of 2.3 times was observed depending on the clinical and morphological form of acute appendicitis, with significantly higher levels in cases of gangrenous and perforated appendicitis." (PMID 38397914, 2024). "In our cohort, children with complicated appendicitis had significantly higher median concentrations of serum IL-6 and IL-10, and lower median concentrations of serum TNF-β compared to children with uncomplicated appendicitis." (PMID 38409170, 2024). "Serum IL-10 and IL-6 were significantly elevated at presentation, and IL-6, IL-8 and TNF-α levels were higher in complicated appendicitis." (PMID 33060696, 2020). "When comparing complicated and uncomplicated appendicitis patients classified according to ICD-9, IL-10 responses towards S. pyogenes, C. albicans, LPS and Pam3Cys were significantly higher in complicated appendicitis patients." (PMID 33060696, 2020). "Correlations between IL-10, IL-6, IL-1Ra and MCP-1 indicate that a combination of these factors could be of importance in appendicitis." (PMID 33060696, 2020).
appendicitis (continued). "Our primary objective was to compare levels of individual inflammatory protein mediators previously associated with intra-abdominal inflammation (CRP, PCT, interleukin-6 (IL-6), IL-8, IL-10, and monocyte chemoattractant protein-1 (MCP-1), SAA) in a cohort of children with suspected appendicitis." (PMID 30918467, 2019). "Similarly, we observed an increase in IL-10 in the appendixes of children with confirmed COVID-19 compared to acute appendicitis and appendixes during non-pandemic periods." (PMID 38397914, 2024). "Significant differences in serum concentrations of IL-6, IL-10, and TNF-β were observed when analyzing cytokine levels between the no appendicitis group, and the uncomplicated and complicated appendicitis groups." (PMID 38409170, 2024).
autoimmune hepatitis (9 papers, 2013 to 2024). Hepatitis caused by autoantibodies. "Recently, studies have reported that Con A-induced autoimmune hepatitis is largely mediated by the release of inflammatory cytokines such as IL-2, IL-4, IL-6, IL-10, IL-12, TNF-α and IFN-γ." (PMID 24498418, 2014). "Similarly, Tregs derived from an autoimmune hepatitis model generated a reduced amount of anti-inflammatory substances (TGF-β and IL-10) compared to control Tregs, associated with impaired CD73 expression on the Treg surface." (PMID 38572243, 2024). "Taking these results together, Con A injection after OLT may induce IL-10-producing Tregs and B-1 cells for the protection and recovery from acute rejection as well as autoimmune hepatitis." (PMID 24454474, 2013). "The mouse experimental autoimmune hepatitis (EAH) model and AIH patients present reduced serum IL-10 and Treg levels." (PMID 34295334, 2021). "In humans with autoimmune liver disease, increased serum levels of the proinflammatory cytokines, IFNγ and IL-17 in AIH and PBC patients were reported, while IL-10 was lower than in healthy controls." (PMID 32849531, 2020).
bacterial meningitis (9 papers, 2007 to 2022). Inflammation of the membranes surrounding the brain and spinal cord due to a bacterial infection. "The expression of IL-6 and IL-10 in the serum of patients with enterovirus/bacterial meningitis is abnormal, while the expression of IL-6 and IL-10 in patients with bacterial meningitis is higher than that of viral meningitis." (PMID 34925324, 2021). "It is assumed that high levels of IL-10, as were observed in CSF from children with bacterial meningitis, can suppress the intensity of intrathecal inflammation and limit its deleterious effects." (PMID 17386119, 2007). "Although it is known that exogenous corticosteroids can improve the outcome of bacterial meningitis, less is known about the role played by important endogenous anti-inflammatory mediators, such as cortisol and IL-10, in CSF during the course of bacterial meningitis." (PMID 17386119, 2007). "Here, exogenous BDNF administration increased IL-10 expression at the transcription and translation levels, suppressed proinflammatory cytokine expression, and enhanced anti-inflammatory cytokine expression in bacterial meningitis models, which was consistent with observations from previous studies." (PMID 28778220, 2017). "The most sensitive ones described in the literature are cytokines such as IL-6, IL-10, TNF-alfa and INF-gamma, which are increased in the CSF of children with bacterial meningitis." (PMID 31063510, 2019). "Plasma concentrations of MCP-1, sCD14, IL-6, and IL-10 were significantly higher in patients with community-acquired pneumonia (CAP; n = 10) and infective endocarditis (IE; n = 11) compared to those with bacterial meningitis (BM; n = 18)." (PMID 29769838, 2018). "Although cortisol has effects similar to those of IL-10, no study of this hormone in the intrathecal compartment during bacterial meningitis has yet been reported in the literature." (PMID 17386119, 2007). "Still, we could not distinguish enteroviral meningitis from bacterial meningitis with the parameters of CSF cytokines IL‐2, IL‐6, IL‐10, TNF, and IFN‐γ." (PMID 31912935, 2020). "Thus, we could not distinguish enteroviral meningitis from bacterial meningitis with the parameters of CSF cytokines IL‐2, IL‐6, IL‐10, TNF, and IFN‐γ." (PMID 31912935, 2020).
bladder tumor (9 papers, 2008 to 2024). "Additionally, PPA@aPD-L1increased IFN-γ and decreased IL-10 expression in bladder tumors, affecting the number and type of intratumorally infiltrating T cells." (PMID 39085255, 2024). "Bladder tumors are often associated with increased regulatory T cell (Tregs) levels, as well as with the expression of inhibitory Th1 response cytokines, such as transforming growth factor-beta (TGF-β) and IL-10." (PMID 38139364, 2023). "The primary bladder tumor cells secrete a large amount of IL-10." (PMID 32655621, 2020). "Bladder tumor cells increase expression of CD206, CD163, PD-L1 and IL10 in macrophages through the secretion of IL10, chemokines, metabolic products, growth factors and micro-RNA via exosome exchange." (PMID 34572939, 2021). "Known characteristics of the MB49luc bladder tumor model include early tumor necrosis and an immunosuppressive (TH2 polarized) TME governed by IL-10 signaling." (PMID 31186063, 2019). "Production of M2 polarizing cytokines such as CCL2, IL-10, and TGF-β by bladder tumors has been demonstrated in various in vitro studies and IL-10 production by bladder tumor cells has been shown to induce an immunosuppressive monocyte phenotype." (PMID 31824850, 2019). "The experimental bladder tumor cell line MB49 does not produce IL-10, which allows examination of its levels to serve as an indicator of local stimulation." (PMID 19040745, 2008).
bronchopulmonary dysplasia (9 papers, 2014 to 2023). Bronchopulmonary dysplasia is a chronic respiratory disease that results from complications related to lung injury during the treatment of infant acute respiratory distress syndrome in low-birth-weight premature infants or from abnormal lung development in older infants. "Additionally, some studies suggest that low levels of venous cord blood IL-10 are associated with an increased risk of suffering moderate or severe bronchopulmonary dysplasia in small, gestational age, preterm newborns." (PMID 37373945, 2023). "Reports about this cytokine show some controversy, and in this sense, high concentrations of IL-10 in serum are related to greater severity of pathologies such as respiratory distress; however, low levels of IL-10 have been associated with an increased risk of developing bronchopulmonary dysplasia." (PMID 32033312, 2020). "MMPs exacerbates secondary inflammation at day 4 after MCAO, and IL-10 can modulate MMPs expression during the development of bronchopulmonary dysplasia." (PMID 37196130, 2023). "Although the mechanisms by which hyperoxia promotes bronchopulmonary dysplasia are not fully defined, the inability to maintain optimal interleukin (IL)-10 levels in response to injury secondary to hyperoxia seems to play an important role." (PMID 26059905, 2015).
Candidemia (9 papers, 2013 to 2025). A form of invasive candidiasis where species of CANDIDA are present in the blood. "An initial elevation of IL-10 was also found to be associated with poor outcomes in other infections, such as Bartonella Quintana bacteremia and candidemia." (PMID 33665221, 2021). "The levels of the anti-inflammatory cytokine IL-10 were significantly higher in the patients with candidemia than in both bacterial infected patients and normal healthy controls." (PMID 34684298, 2021). "In a large prospective cohort of ICU patients with candidemia, polymorphisms in cytokine genes encoding IL-10 and IL12B were found to be associated with persistent candidemia." (PMID 29371502, 2018). "The −1082A/G polymorphism in the anti-inflammatory cytokine gene IL-10 and the 274INS/DEL polymorphism in IL-12b, are associated with persisting candidemia." (PMID 23629947, 2013). "Two polymorphisms, one in IL10 and one in IL12B, are associated with persistent candidemia, but not candidemia in general." (PMID 32185141, 2020).
chronic granulomatous disease (9 papers, 2015 to 2025). Chronic granulomatous disease (CGD) is a rare primary immunodeficiency, mainly affecting phagocytes, which is characterized by an increased susceptibility to severe and recurrent bacterial and fungal infections, along with the development of granulomas. "On the other hand, hematopoietic stem cell transplantation may cure some of the known monogenic diseases such as interleukin 10 abnormalities, X-linked lymphoproliferative disorder type 2, or chronic granulomatous disease." (PMID 31429721, 2019). "In a model of murine chronic granulomatous disease pioglitazone increased TGFβ and IL-10 while decreasing KC (mouse homologue to IL-8), IL-6, and TNFα expression." (PMID 26713087, 2015).
coagulopathy (9 papers, 2019 to 2023). "TF level was also positively correlated with TNF-α, IL-1β, IL-6, and MPO levels and was negatively correlated with IL-10, indicating that the TF level was closely associated with the inflammatory factors, which may cause coagulation disorders." (PMID 32587471, 2020). "IL-10 KO mice infected with P. chabaudi were used to investigate dynamics of coagulopathy and microgliosis." (PMID 37945689, 2023). "The current study was carried out to investigate the roles of microglia in relation to vascular dysregulation, specifically coagulopathy, with studies conducted in a P. chabaudi model in IL-10 KO CX3CR1-GFP CCR2-RFP mice." (PMID 37945689, 2023). "The current studies have mostly focused on IL-6, and the role of IL-10 in endothelial homeostasis and coagulation disorders needed further investigation." (PMID 37814134, 2023). "Elevated C-reactive protein (CRP), ferritin, INF-γ and IL-10 levels accompanied by grade 3 coagulopathy with hypofibrinogenemia were subsequently observed." (PMID 35317863, 2022). "In univariable analysis, sex, clinical classification, IL-2R, IL-10, TNF-α, PCT, neutrophil percentage, lymphocyte percentage, NT-proBNP, hs-cTnI, eGFR, coagulation disorder, and D-dimer were associated with AKI." (PMID 32850917, 2020). "Additionally, in univariable analysis, sex, IL-2R, IL-10, TNF-α, neutrophil percentage, lymphocyte percentage, NT-proBNP, hs-cTnI, coagulation disorder, and D-dimer were associated with kidney injury." (PMID 32850917, 2020). "Thus, the presence of IL-10 in the hyperinflammation process may contribute to the development of coagulation disorders and thrombotic events." (PMID 37112918, 2023). "Accompanying supplemental S1b-e IVM videos of the infected IL-10 KO show examples of the types of altered blood flow such as changes in speed and direction that occur during coagulopathy, and disruption to the vascular integrity in which microhemorrhages may be appreciated." (PMID 37945689, 2023).
contact dermatitis (9 papers, 2008 to 2025). An inflammatory skin condition caused by direct contact between the skin and either an irritating substance or an allergen. "Research has shown that LCs induce CD4+ regulatory T lymphocytes, and promote tolerance in CD8+ T lymphocytes, and cause production of IL-10 by Langerhans cells which suppress contact dermatitis." (PMID 38500882, 2024). "The treatment of mice subjected to contact dermatitis with polyphenols from pomegranate was followed by increasing splenic IL-10-producing and IFN-γ-/IL-4-producing CD4+ T cells." (PMID 36431972, 2022). "In the context of contact dermatitis, dexamethasone-treated DCs from the peripheral blood of individuals with IgE-mediated latex allergy restrain allergen-specific T cell proliferation and IgE production in vitro and induce the generation of IL-10-producing Tregs." (PMID 33114551, 2020). "RT-PCR analyses also revealed mRNA upregulation of pro-inflammatory cytokines (IL-1β and IL-6) and some Th1 or Th2 cytokines (IFNγ, IL-4, and IL-10), but not that of IL-2, TGFβ, and IL-17, at the delayed phase of oxazolone-induced contact dermatitis, similar within the three genotypes." (PMID 36768979, 2023).
fibromyalgia (9 papers, 2017 to 2025). A chronic disorder of unknown etiology characterized by pain, stiffness, and tenderness in the muscles of neck, shoulders, back, hips, arms, and legs. "This study aims to investigate the effects of resistance training (RT) before hyperalgesia induction on pain sensitivity, IL-6 and IL-10 expression in skeletal muscle, and thalamic serotonin levels in a fibromyalgia (FM)-like rat model." (PMID 40566503, 2025). "A recent systematic review and meta-analysis of 29 studies (N=2458) reported significant increases of TNF, IL-6, IL-8 and IL-10 in CWP/fibromyalgia patients compared with healthy controls." (PMID 39231552, 2024). "On the contrary, in patients with fibromyalgia, plasma IL-10 showed a blunted response and IL-8 seem to decrease." (PMID 28243900, 2017). "Contrary, in TMD patients with widespread pain and in fibromyalgia plasma levels of pro-inflammatory IL-8 were higher and IL-10 lower than controls." (PMID 28243900, 2017). "The cytokines IL-6 and IL-10 were selected because they represent key pro- and anti-inflammatory mediators involved in the nociceptive sensitization and immune dysregulation observed in fibromyalgia." (PMID 40566503, 2025). "However, the most recent meta-analysis of fibromyalgia examined nine biomarkers and found some evidence of differences between cases and controls for seven of them, including IL-10, IL-6, IL-8, TNF-alpha, IFN.gamma, and CRP, which are associated with the inflammatory process." (PMID 40001459, 2025). "However, serum IL-10 showed a blunted response to exercise in fibromyalgia." (PMID 28243900, 2017). "Fibromyalgia patients exhibited a reduction in anti-inflammatory IL-10 levels within a time frame of 8 weeks in usual care, while MBSR intervention successfully maintained IL-10 levels after 8 weeks (n = 70)." (PMID 35682203, 2022).
iron deficiency (9 papers, 2010 to 2025). "This polymorphism was associated with a high risk of having interleukin 10 <p25 and magnesium deficiency in controls." (PMID 35625529, 2022). "While levels of TNF, IFN-γ and IL-1β (type I) and IL-10 and IL-13 (type II) seemed decreased in iron deficiency anaemia, the levels of IL-12 and IL-5 appeared increased." (PMID 20546583, 2010). "On the other hand, there was strong evidence that the slopes of regression lines for the association between IFN-γ and IL-10 differed with iron deficiency anaemia status (P = 0.001)." (PMID 20546583, 2010). "Iron deficiency anaemia was associated with increased TNF production in infected individuals and overall with increased IL-10 production, while magnesium deficiency induced increased production of IL-10 by 46% (13% to 144%) in uninfected donors." (PMID 20470442, 2010). "Magnesium deficiency, on the other hand, seemed to associate with higher concentrations of IL-10 in donors uninfected at time of blood collection." (PMID 20470442, 2010). "However, IL-10 levels with the LPS stimulus were significantly different between supplementation and deficiency diets (p = 0.049), and iron deficiency inhibited the secretion of this cytokine." (PMID 39166620, 2024). "Indeed, IL-12/IL-10 ratio in response to LPS was significantly increased under iron deficiency, suggesting a pro-inflammatory role of iron deficiency in macrophages." (PMID 29771935, 2018). "Indeed, the gene expression of Arg1, Ym1, IL-10 and Stat6, a series of genes expressed in M2 polarized macrophages, was increased after high iron diet condition, and, conversely, the expression of Arg1 and IL-10 was significantly decreased after dietary iron deficiency." (PMID 29771935, 2018). "There was a tendency, albeit not significant, that iron deficiency anaemia (IDA) influenced the relationship between concentrations of TNF and IL-10, as indicated by the difference between slopes of 119% (35% to 637%; 95% CI, P = 0.20)." (PMID 20470442, 2010). "Magnesium deficiency seemed to be associated overall with low TNF concentrations, low concentrations of IL-1β and higher concentrations of IL-10 in uninfected but not infected donors." (PMID 20470442, 2010).